METTL3 (methyltransferase 3, N6-adenosine-methyltransferase complex catalytic subunit)
Diseases named in the same sentence as METTL3 in open-access papers (continued):
Sharing a sentence is not in itself a finding about the gene and the disease.
tumor (continued). "Elevated METTL3 expression promotes tumor growth and glycolysis in CCA through m6A modification of AKR1B10, indicating that METTL3 is a potential target for blocking glycolysis for application in CCA therapy." (PMID 36476503, 2022). "It has been reported that METTL3 deletion enhances the activation of NF-κB and STAT3 indirectly, leading to tumor growth and metastasis." (PMID 35874897, 2022). "METTL3 and METTL14 cooperate to promote m6A RNA modification, but they have been reported to demonstrate opposite effects on the occurrence of the same tumor." (PMID 36561529, 2022). "We then measured the expression level of METTL3 in tumor tissues of 96 ICC patients by immunohistochemistry (IHC) staining and compared the correlation between METTL3 expression and clinical characteristics." (PMID 35094011, 2022). "Like METTL3, METTL14 has been shown to act both as a tumour suppressor and an oncogene in regulating the development of a number of different tumour types." (PMID 36733939, 2022). "Interestingly, overexpression of HHLA2 in the METTL3-depleted model could significantly reverse and promote the tumor growth of 786-O cells (P < 0.0001), suggesting that HHLA2 overexpression could reverse the inhibition of tumor growth induced by METTL3 depletion." (PMID 35794583, 2022). "When we used TCGA pancancer data to analyze the expression levels of the model’s key genes, METTL3 and IFIT2 were observed to have extensively different expression levels in regular and tumor tissues." (PMID 36386128, 2022). "In a couple of solid tumors, the other group and we have uncovered beneficial roles for regulators, such as METTL3 and YTHDF2, in the immune response to tumor cells by NK cells." (PMID 35296338, 2022). "The excessive tumor growth induced by METTL3 upregulation was blocked by FRAS1 or YTHDF1 knockdown, including tumor volume and tumor weight." (PMID 36008805, 2022). "According to recent literature, HBXIP drives the metabolic reprogramming of HCC through METTL3-mediated m6A methylation of HIF-1α, which stimulates the Warburg effect and tumor cell survival." (PMID 35794625, 2022). "In CC, the expression of METTL3 and CD33+ MDSCs in tumor tissues is higher than that in adjacent normal tissues, and their expression is positively correlated." (PMID 36071523, 2022). "We next examined METTL3 and ALKBH5 expressions in the specimens with a tumor/adjacent tissue global m6A ratio of more than 1.5." (PMID 35078505, 2022). "METTL3 interacts directly with the 5′/3′UTR region of HK2 and the 3′UTR region of GLUT1 to activate the glycolytic pathway and prevents tumor apoptosis by stabilizing the transcriptional translation of these two genes." (PMID 35794625, 2022). "METTL3 knockdown of HEPG2 and Huh7 cells slows cell proliferation, reduces colony formation, suppresses cell migration and impairs in vivo tumor formation." (PMID 36008936, 2022). "Methyltransferase-like 3 (METTL3), a crucial m6A regulatory enzyme, governs the process of m6A methylation, thereby regulating the tumor formation and development by affecting mRNA stability, translation, or degradation." (PMID 35255776, 2022). "From above all, METTL3, YTHDF1/2/3, ALKBH5 play positive role in the occurrence and development of OC, while FTO is a tumor suppressor." (PMID 35813486, 2022). "Conversely, a separate study suggested that METTL3 was upregulated in GBM tumors and its knockdown inhibited tumor growth in U87/shMETTL3-injected mice." (PMID 36008936, 2022). "Previous study reported that METTL3 is downregulated in PTC tissues and plays a tumor-suppressor role." (PMID 35436987, 2022).
tumor (continued). "For example, METTL3 is upregulated in breast cancer, which increases hepatitis B X-interacting protein (i.e., HBXIP) mRNA methylation and stability, inducing tumor cell proliferation and survival by inhibiting the tumor suppressor, let −7 g." (PMID 35571068, 2022). "To verify the relationship between METTL3, FGFR3 and antitumor sensitivity of anlotinib in vivo, we explored the expression level of METTL3 and FGFR3 of tumor tissues from eight previously established OSCC PDX models." (PMID 36167542, 2022). "Here, we identified METTL3 as a pivotal regulator in ESCC, which promoted the development of tumor proliferation and metastasis." (PMID 35399719, 2022). "METTL3 also regulates integrin subunit beta 1 (ITGB1) expression, thereby affecting the binding of ITGB1 to collagen I. This disruption affects tumor cell migration and promotes bone metastasis in prostate cancer." (PMID 35571068, 2022). "In brief, METTL3 overexpression in GC promoted the m6A modification of ADAMTS9, a tumor-suppressor gene, and epigenetically prevented its transcription in a YTHDF2-dependent manner." (PMID 35574388, 2022). "Methyltransferase-like 3 (METTL3), a methyltransferase responsible for the methylation of N6 methyladenosine (m6A), has been found to be involved in the sensitivity of tumor cells to cisplatin and the proliferation and metastasis of NSCLC cells." (PMID 36408273, 2022). "β-elemene can reduce the level of m6A modification of PTEN mRNA by downregulating the expression of METTL3, resulting in an increase in the expression of PTEN protein, which ultimately inhibits the growth of tumor cells and promotes apoptosis." (PMID 35784761, 2022). "Several studies have demonstrated that m6A modulators (e.g., METTL3 and WTAP) affect tumor glucose metabolism by regulating glycolytic enzymes (Warburg effect) to promote proliferation." (PMID 35794625, 2022). "Mechanistic studies suggested that deletion of METTL3 disrupted YTHDF1-mediated SPRED2 translation, thereby enhancing NF-kB and STAT3 activation via the ERK pathway, leading to tumor progression." (PMID 36035182, 2022). "By inserting these modifications in the mRNA of JAK1, lactylated METTL3 strengthens the pro-tumoral JAK/STAT3 pathway and enhances tumor progression of colon cancer both in vitro and in vivo." (PMID 36226054, 2022). "An added value of Tassinari’s work is that METTL3 main targets ADAR1 and eventually leads to modulating cell proliferation and tumor growth." (PMID 35462896, 2022). "In this study, METTL3/YTHDF1 elevated FRAS1 protein expression, thus accelerating cell proliferation and tumor growth (colony formation)." (PMID 36008805, 2022). "METTL3-catalyzed m6A modifications of the SET domain-containing 7 (SETD7) and kruppel-like factor 7 (KLF7) mRNAs, which function as tumor suppressors, are recognized by YTHDF2 for mRNA decay." (PMID 36226062, 2022). "For example, METTL3/IGF2BP3 axis mediated m6A modification of PD-L1 mRNA and mobilized infiltrating immune cells to resist tumor progression." (PMID 36105819, 2022). "To further validate the results, we obtained 60 paired tumor tissues and adjacent normal tissues of ESCC, and qRT-PCR was used to determine the expression pattern of METTL3, METTL14, WTAP, FTO, ALKBH5, YTHDF1 and YTHDF2." (PMID 35399719, 2022). "Although METTL3, METTL14 and WTAP can form RNA methyltransferase complexes, which regulate the fate of tumour development, studies have shown that METTL3 and METTL14 also have independent regulatory functions in regulating transcription." (PMID 36434140, 2022). "With the development of high-throughput sequencing, sporadic studies have revealed that m6A regulators METTL3, FTO, and HNRNPA2B1 are aberrantly expressed in EC and affect the metastasis and invasion of a tumor by affecting the stability of mRNA." (PMID 36364436, 2022).
tumor (continued). "Patient-derived tumor xenograft (PDX) models and immunohistochemistry staining were performed to study the relationship of METTL3 and antitumor sensitivity of anlotinib in vivo." (PMID 36167542, 2022). "For example, METTL3 can regulate the dynamic balance and differentiation of T cells, and YTHDF1 can regulate the number of CD8+ T cells infiltrated in tumor microenvironment in mice." (PMID 35590394, 2022). "METTL3, a m6A “writer’’, can activate the JAK/STAT pathway which leads to immunosuppression of TME and tumor progression." (PMID 36319992, 2022). "Various m6A methylation enzymes, such as METTL3, FTO, and ALKBH5, clearly affect key cellular processes in tumor cells, including apoptosis, resulting in resistance to radiation therapy." (PMID 35794625, 2022). "Overall, these results showed that the expression of METTL3, METTL14, and WTAP were higher in tumor samples than in the adjacent normal samples." (PMID 35778697, 2022). "METTL3, METTL14, METTL16, YTHDC1, YTHDC2, and ZC3H13 expression levels were significantly greater in tumor tissues (p < 0.05)." (PMID 36091006, 2022). "Some m6A regulators are abnormally expressed in OC, such as YTHDF1, YTHDF2, METTL3, ALKBH5 etc., and promote or disrupt the development or maintenance of tumour phenotypes." (PMID 35303965, 2022). "The expression levels of METTL3 and IGF2BP2 were also significantly decreased in RCC tumor tissues compared to normal tissues." (PMID 36591524, 2022). "For instance, METTL3 and METTL14, as methylating enzymes, regulate a variety of malignant events, including tumor proliferation, metastasis, stemness maintenance, and chemotherapy resistance." (PMID 36438800, 2022). "Studies have shown that METTL3 is highly expressed in NSCLC and promotes the occurrence and development of NSCLC by promoting tumor cell proliferation, EMT, invasion, metastasis, angiogenesis, and anti-apoptosis." (PMID 35784761, 2022). "To confirm the role of METTL3/FRAS1 axis in vivo, we verified its effects on tumor growth using xenograft tumor model." (PMID 36008805, 2022). "METTL3 increases the methylation and stability of HBXIP mRNA by inhibiting the expression of the tumor suppressor gene let-7g in breast cancer, thereby inducing cell proliferation and survival." (PMID 36360287, 2022). "Overall, METTL3, METTL14, VIRMA, and ALKBH5 immunoexpression levels differed significantly between tumor and normal tissues." (PMID 35048498, 2022). "Besides, innate immunity activation is important for the initiation of anti-tumor immunity, therefore, it might be a potential strategy for targeting METTL3 to enhance the immunogenicity of solid tumors and promote innate immunity-induced T-cell infiltration in tumors." (PMID 33707441, 2021). "Our results have revealed a novel mechanism of Mettl3 by which it mediates m6A modulation of TEK and VEGF-A to promote tumor angiogenesis." (PMID 33681207, 2021). "Functionally, knockdown of METTL3 significantly repressed CRC cell proliferation and migration in vitro, while its overexpression accelerated CRC tumor formation and metastasis both in vitro and in vivo." (PMID 33411363, 2021). "Inhibiting the expressions of m6A methyltransferase METTL3 or METTL14 can reduce the m6A level and promote the tumor formation ability of GSCs in vivo." (PMID 34281602, 2021). "In GC, METTL3 has been recognized as a potential prognostic marker, promoting the malignant phenotype of GC cells and metastasis via EMT and tumor angiogenesis." (PMID 34842045, 2021). "The levels of METTL3 and METTL14 in AML show significant changes, which affects the proliferation of AML cells and the process of tumor progression." (PMID 34206803, 2021). "Moreover, Snail could promote tumor invasion and metastasis under the regulation of METTL3." (PMID 33879256, 2021). "Therefore, targeting METTL3 may be regarded as a promising approach of tumor targeted therapy." (PMID 33879256, 2021).
tumor (continued). "METTL3 inhibits the expression of SOCS2 through an m6A-YTHDF2-dependent mechanism, which leads to tumour development." (PMID 34246319, 2021). "Meanwhile, we found that the expressions of METTL3, METTL14, WTAP, and YTHDF1-3 proteins were significantly lower in the stroma cells than that in the tumor cells." (PMID 34733841, 2021). "Here the authors show that N6-methyladenosine methylation writer METTL3 downregulates APC by recruiting YTHDF2 for APC mRNA degradation, and that this promotes glycolysis and tumour growth in oesophageal cancers." (PMID 34155197, 2021). "METTL3-induced increases in lncRNA ABHD11-AS1 expression promotes the proliferation and Warburg effect of tumor cells." (PMID 34416901, 2021). "METTL3, VIRMA, and hnRNPC showed higher expression in tumor samples, while METTL14, ZC3H13, FTO, ALKBH5, YTHDF2, YTHDC1, and YTHDC2 showed higher expression in normal tissue samples 53,152,156,157." (PMID 33390849, 2021). "For example, three independent studies showed that METTL3 acted as an oncogene in CRC, whereas METTL3 can also play a tumor suppressive role in CRC." (PMID 33411363, 2021). "For discovering the role of METTL3 in OSCC, we evaluated the effects of METTL3 on CD8+ T cell activation and tumor cell phenotypes." (PMID 34476262, 2021). "Like the m6A writer proteins METTL3 and METTL14, the m6A reader proteins YTHDF1 and YTHDF2 can act as either an oncogene or a tumor suppressor." (PMID 33922187, 2021). "However, little is known about whether METTL3 participates in tumor immunity in NSCLC." (PMID 34416901, 2021). "Another study showed that deletion of METTL3/m6A leads to suppression of IL-2-STAT5 signaling pathway, which controls Treg cell functions and regulates the tumor-killing functions of CD8 T cells." (PMID 33922187, 2021). "To further investigate the impact of METTL3 on the tumour microenvironment, we analysed CD45+ cells in tumours from WT or KO mice through single-cell RNA sequencing." (PMID 33654093, 2021). "CRISPR/Cas13b-METTL3 targeting LncRNA NEAT1 m6A methylation activates LncRNA NEAT1 expression and suggested its potent tumor-suppressive function." (PMID 34957107, 2021). "On the contrary, METTL3, KIAA1429, RBM15B, HNRNPA2B1, and HNRNPC had significantly higher expression in tumor tissues (p < 0.001)." (PMID 34277622, 2021). "RT-qPCR and immunoblotting analysis showed that METTL3 overexpression elevated the expression of miR-221-3p and Che-1 but diminished the expression of HIPK2 in mouse tumor tissues after ADR treatment." (PMID 33420414, 2021). "METTL3 enhances metastasis of GC by m6A modification of ZMYM1/E-cadherin signaling, and WTAP results in a poor clinical prognosis of GC through regulating tumor-related immune infiltration." (PMID 33791305, 2021). "Aberrant expression of m6A methyltransferase METTL3 increased m6A methylation and total mRNA level of LEF1, resulting in the activation of Wnt/β-catenin signaling pathway and accelerated tumor progression." (PMID 35186011, 2021). "RNA m6A modification and its key m6A methyltransferase METTL3, which forms a heterodimer with METTL14, have been reported to be essential for tumour progression in several types of cancer." (PMID 34155197, 2021). "Overexpression of hexokinase 2 (HK2) and GLUT1 was attributed to the METTL3-m6A-IGF2BP2/3-dependent mechanism and further accelerated glycolysis to accelerate tumor growth." (PMID 33879256, 2021). "Hypermethylation of RDM1 induced by METTL3 suppressed the expression of RDM1, leading to the activation of the Ras/Raf/ERK pathway in tumor progression." (PMID 33879256, 2021). "METTL3 enhanced the stability of pyruvate dehydrogenase kinase 4 (PDK4) and HK2 mRNAs in a METTL3-m6A-YTHDF1-dependent manner, ultimately promoting tumor growth and chemoresistance." (PMID 33879256, 2021).
tumor (continued). "Mechanistically, METTL3 regulated the expression of the HNF1 homeobox A (HNF1A) in a METTL3-m6A-IGF2BP2-dependent manner, eventually enhancing the migratory ability of tumor cells and activating the Wnt pathway." (PMID 33879256, 2021). "Our findings reveal that METTL3 positively regulates FBXW7 expression and confirm the tumor-suppressive role of m6A-modified FBXW7, thus providing insight into its epigenetic regulatory mechanisms in LUAD initiation and development." (PMID 33676554, 2021). "In accordance with our results, METTL3, YTHDF2, and YTHDF1 were found to be considerably overexpressed between tumor and normal adjacent tissues." (PMID 34248650, 2021). "We found that METTL3, RBM15B, YTHDC2, YTHDF2, and HNRNPA2B1 were indeed highly expressed in the tumor samples." (PMID 34336856, 2021). "High METTL3 level seems to facilitate GC progression and metastasis by promoting epithelial–mesenchymal transition (EMT) and tumor angiogenesis." (PMID 34842045, 2021). "(iii) More relevantly, CISH has been shown in maintaining T-cell homeostasis via Mettl3-mediated methylation mechanism and (iv) The m6A-reader protein ‘YTHDF2’ is involved in controlling NK cell-mediated anti-tumour immunity." (PMID 34207299, 2021). "To investigate the clinical significance of METTL3 expression in ESCC, we used IHC to examine METTL3 expression in 101 tumor tissues and 53 adjacent normal tissues." (PMID 34094960, 2021). "Specifically, HNRNPC, YTHDF1, YTHDF2, METTL3, RBM15, YTHDF3, and KIAA1429 are highly expressed in tumor tissues." (PMID 32258108, 2020). "Hence, METTL3 might function as a tumor suppressor in the tumorigenesis of RCC." (PMID 33015074, 2020). "In the present study, we detected the levels of METTL3 and CD33+ MDSCs in tumour specimens from 197 CC patients by immunohistochemical (IHC) staining." (PMID 33059689, 2020). "Five m6A-related genes (ZC3H13, METTL14, YTHDF2, YTHDF3 and HNRNPA2B1) showed significantly downregulated in tumor tissue, while seven regulators (YTHDC2, FTO, WTAP, METTL3, ALKBH5, RBM15 and KIAA1429) was remarkably upregulated in ccRCC." (PMID 32419773, 2020). "In summary, different components of the m6A “writer” complex have been reported to play either oncogenic or tumor suppressive roles during HCC progression, but the majority of these findings support the oncogenic role of METTL3 in human HCC." (PMID 32111216, 2020). "HBXIP promotes METTL3 expression through inhibiting tumour suppressor, miRNA let‐7g that targets the 3′‐UTR of METTL3 mRNA." (PMID 33029866, 2020). "Intriguingly, the expression levels of both METTL3 and ALKBH5 are elevated in GSCs, with opposite results on m6A-mediated tumor formation in a target-specific manner." (PMID 32404927, 2020). "Altogether, our studies showed that, besides the known tumor‐promoting effect in HCC, METTL3 can activate mTORC1 pathway and promote glycolysis in HCC cells." (PMID 32068977, 2020). "The results revealed that METTL3 and IGF2BP2 were significantly upregulated in tumor tissues compared with those in adjacent normal tissues." (PMID 33224879, 2020). "Increased METTL3 levels and CD33+ MDSCs have been found in tumour microenvironments and lead to a poor prognosis." (PMID 33059689, 2020). "We found that tumour tissues displayed increased levels of METTL3 and CD33+ MDSCs compared with tumour-adjacent tissues from the same CC patients." (PMID 33059689, 2020). "Silencing METTL3 expression reduces SOX2 expression and, as a result, inhibits GBM tumor growth and prolongs the survival of mice." (PMID 32404927, 2020). "METTL3 also catalyzes m6A modifications in the mRNAs of SETD7 and KLF4, two tumor suppressors that are part of the METTL3/YTHDF2-SETD7/KLF4 m6A axis." (PMID 32765970, 2020).